CLTA (clathrin light chain A)
Description:
Clathrin is the major protein of the polyhedral coat of coated pits and vesicles. Acts as a component of the TACC3/ch-TOG/clathrin complex proposed to contribute to stabilization of kinetochore fibers of the mitotic spindle by acting as inter-microtubule bridge.
Synonyms: Lca
Tractability: Antibody: its Gene Ontology location is reachable by antibodies, with high confidence; UniProt places it where antibodies can reach, with medium confidence. PROTAC: ubiquitination databases record sites on it; its protein half-life has been measured.
Target class: Structural protein
Gene: Protein-coding gene on chromosome 9 (36,190,856 to 36,304,781, forward strand). Ensembl gene ENSG00000122705.
Subcellular location: Cytoplasmic vesicle membrane; Membrane, coated pit; Cytoplasm, cytoskeleton, spindle
Subcellular location (Human Protein Atlas): Endosomes; Lysosomes; Golgi apparatus; Mitotic spindle; Plasma membrane; Primary cilium
Pathways (Reactome):
Vesicle-mediated transport: Cargo recognition for clathrin-mediated endocytosis; Clathrin-mediated endocytosis; Formation of annular gap junctions; Gap junction degradation; Golgi Associated Vesicle Biogenesis; Lysosome Vesicle Biogenesis
Signal Transduction: Retrograde neurotrophin signalling; WNT5A-dependent internalization of FZD2, FZD5 and ROR2; WNT5A-dependent internalization of FZD4
Developmental Biology: EPH-ephrin mediated repulsion of cells; Recycling pathway of L1
Transport of small molecules: LDL clearance; VLDLR internalisation and degradation
Disease: Entry of Influenza Virion into Host Cell via Endocytosis
Immune System: MHC class II antigen presentation
Gene Ontology:
Molecular function: clathrin heavy chain binding; protein binding; GTPase binding; peptide binding; protein-containing complex binding; structural molecule activity
Biological process: clathrin coat assembly; chromosome segregation; clathrin coat disassembly; clathrin-dependent endocytosis; mitotic cell cycle; mitotic spindle organization; endocytosis; intracellular protein transport; synaptic vesicle endocytosis; vesicle-mediated transport
Cellular component: clathrin coat; clathrin complex; endosome; lysosome; membrane; plasma membrane; clathrin vesicle coat; clathrin-coated endocytic vesicle; cytoplasmic vesicle; cytosol; endolysosome membrane; kinetochore microtubule; mitotic spindle microtubule; synaptic vesicle membrane; trans-Golgi network membrane; clathrin coat of coated pit; clathrin coat of trans-Golgi network vesicle; clathrin-coated pit; clathrin-coated vesicle; cytoplasmic vesicle membrane; postsynaptic endocytic zone; presynaptic endocytic zone membrane; spindle
Genetic constraint (gnomAD): Loss-of-function variants: 5 observed, 19.26 expected, observed/expected ratio (o/e) 0.26, 90% interval 0.14 to 0.55. The upper end of that interval is the gene's LOEUF score, 0.55, which puts it in group 2 of 6, group 1 being the genes least tolerant of losing a copy. Missense variants: 253 observed, 247.4 expected, observed/expected ratio (o/e) 1.02, 90% interval 0.92 to 1.13. Synonymous variants: 110 observed, 100.51 expected, observed/expected ratio (o/e) 1.09, 90% interval 0.94 to 1.28.
Homologues: Orthologues: macaque CLTA (100% identical), chimpanzee CLTA (99% identical), mouse Clta (99% identical), dog CLTA (99% identical), rabbit CLTA (98% identical), rat Clta (98% identical), guinea pig CLTA (96% identical), pig CLTA (95% identical), tropical clawed frog clta (75% identical), zebrafish clta (70% identical), Drosophila melanogaster Clc (37% identical), Caenorhabditis elegans clic-1 (27% identical). Paralogues in human: CLTB (59% identical).
Diseases named in the same sentence as CLTA in open-access papers:
CLTA is named in the same sentence as 12 diseases in open-access papers, as found by Europe PMC text mining. Sharing a sentence is not in itself a finding about the gene and the disease. The quoted sentences say what the papers report.
melanoma (3 papers, 2013 to 2023). A malignant, usually aggressive tumor composed of atypical, neoplastic melanocytes. "Anti‐CTLA‐4 monotherapy was associated with longer OS for patients with melanoma, whereas anti‐PD‐L1 + anti‐CLTA‐4 combination therapy were associated with longer OS for NSCLC and RCC." (PMID 37962239, 2023). "Based on our data, we recommend the use of a combined geometric mean of the expression levels of CLTA, MRPL19 and ACTB for normalization of gene expression in FFPE melanomas." (PMID 31567589, 2020). "To test if these human orthologs are involved in endocytosis, we co-localized 30 of them with clathrin light chain A (CLTA), a marker of the major internalization pathway—clathrin-mediated endocytosis, in a human melanoma cell line." (PMID 23549480, 2013). "We recommend using a geometric mean of the expression of CLTA, MRPL19 and ACTB for normalization of gene expression in melanomas and a geometric mean of the expression of CASC3 and RPS2 for normalization of gene expression in melanoma cell lines." (PMID 31567589, 2020).
Autoimmunity (1 paper, 2010). The occurrence of an immune reaction against the organism's own cells or tissues. "Our investigation into the association of CLTA-4 polymorphisms and the results of interferon therapy in a population where the occurrence of autoimmunity has been rigorously prospectively characterized, assumes that the predominant effect of CTLA-4 polymorphisms is upon T-cell responsiveness." (PMID 21044351, 2010).
glioma (1 paper, 2008). A benign or malignant brain and spinal cord tumor that arises from glial cells (astrocytes, oligodendrocytes, ependymal cells). "CLTA and TPD52L2 had clear, verifiable glioma-specific splicing patterns by both exon array and RT-PCR; they were also listed in one of these reports." (PMID 18474104, 2008). "In total, we confirmed 14 genes with glioma-specific splicing; seven were novel events identified by the exon expression array (A2BP1, BCAS1, CACNA1G, CLTA, KCNC2, SNCB, and TPD52L2)." (PMID 18474104, 2008).
haemorrhoid (1 paper, 2020). "However, the results showed that the expression levels of all important node genes (CLTA, CLTC, RAB3A, SNAP25, SYT1, VAMP2) on Synaptic vesicle cycle pathways from haemorrhoid patient samples were lower significantly than them from healthy tissue samples." (PMID 32620169, 2020).
hepatocellular carcinoma (1 paper, 2023). A malignant tumor that arises from hepatocytes. "The present study aimed to elucidate the role of clathrin light chain A (CLTA) in sEV uptake in hepatocellular carcinoma (HCC)." (PMID 37354358, 2023).
liver cancer (1 paper, 2023). An epithelial or non-epithelial malignant neoplasm that arises from the liver. "Additionally, CLTA was found to be overexpressed in liver cancer cells, which ranked 5th among the 40 cell types examined." (PMID 37354358, 2023).
migraine (1 paper, 2019). "Other peptides with significantly different levels within our migraine or OIH models were derived from functionally distinct proteins such as SCG, proSAAS, Thymosin-β, Acidic nuclear phosphoprotein, Tubulin-β, Clathrin light chain A, and mast cell protease." (PMID 31649062, 2019).
viral infection (1 paper, 2025). "To analyze the role of the interacting proteins during viral infection, we examined previously published proteomic databases and found that EEF2, ANXA1, ANXA5, SLADRA, CLTA, and FTH1 were significantly enriched and FTH1 was notably upregulated in ASFV-infected PAMs." (PMID 40661982, 2025).
tumor (5 papers, 2017 to 2024). "Also, an anti-CTLA-4 DNA aptamer and a dual function aptamer (anti-CTLA-4/PD-L1) have shown that an anti-CLTA-4 aptamer can promote T lymphocyte proliferation, inhibit tumor growth, and strengthen anti-tumor immunity." (PMID 38473398, 2024). "CLTA could be detected in the total cell lysates of PDX tumor, implicating the physiological relevance of this model to study the function of CLTA." (PMID 37354358, 2023). "In another tissue microarray consists of normal liver tissues, early-stage HCC tissues and late-stage HCC tissues, we observed that CLTA immunoreactivity was remarkably higher in tumor tissues than in normal liver tissues and progressively increased from the early to late tumor stage." (PMID 37354358, 2023). "Moreover, CLTA inhibitor Pitstop 2 alone or in combination with sorafenib could inhibit patient-derived xenografts (PDXs) tumor growth." (PMID 37354358, 2023). "While the opposite was observed in tumor cells, with PRC2 up-regulation leading to down-regulation of PD-L1, it is interesting to see that anti-CLTA-4 immune checkpoint inhibitor therapy is actually improved when given in conjunction with EZH2 therapies." (PMID 39689157, 2024). "The Cancer Genome Atlas (TCGA) and GTEx databases showed that CLTA was the only CLT subunit that was significantly upregulated in HCC tumor tissues (n = 369) compared to noncancerous liver tissues (n = 160)." (PMID 37354358, 2023). "Selumetinib, whether as monotherapy or in combination with anti-CLTA-4, did not change the percentage of IFNγ-producing T-cells within total splenocytes and tumor samples, following ex-vivo stimulation with anti-CD3, when compared to control or anti-CTLA-4 antibody alone (data not shown)." (PMID 28807001, 2017).
infection (3 papers, 2013 to 2020). The state of being infected such as from the introduction of a foreign agent such as serum, vaccine, antigenic substance or organism. "Then, we checked the abundance level of cytotoxic T-lymphocyte-associated protein 4 (CTLA-4) and clathrin light chain A (CLTA) by Western blot, noting that CLTA was more abundant in infected animals whereas CTLA4 showed reduced levels after infection." (PMID 24308825, 2013). "In addition, CLTA is mandatory for the entry of enterovirus 71 (EV71) via clathrin-mediated endocytosis, and the blocking with chlorpromazine inhibited the infection of RD cells by 80%." (PMID 33321840, 2020).
cancer (2 papers, 2023). A tumor composed of atypical neoplastic, often pleomorphic cells that invade other tissues. "Here, we revealed the functions of CAPG, together with CLTA, in regulating the internalization of sEVs by cancer cells." (PMID 37354358, 2023). "Anti-cancer-activity-related proteins were altered, including CLTA, HSPA9, HIST2H2BF, KRT18, HINT1, DSP, and VIM." (PMID 37371778, 2023).
CLTA also shares sentences with these, for which no sentence is quoted: Hernia (1 paper).